HK2 (hexokinase 2)
Diseases named in the same sentence as HK2 in open-access papers (continued):
Sharing a sentence is not in itself a finding about the gene and the disease.
cervical squamous cell carcinoma (8 papers, 2020 to 2024). A squamous cell carcinoma arising from the cervical epithelium. "Increased levels of HK2 are closely linked to increased radiation therapy sensitivity in cervical squamous cell carcinoma and can serve as a reliable predictor of this cancer type." (PMID 39224810, 2024). "Additionally, the positive correlation between HK2 and Akt1 expression in cervical squamous cell carcinoma and endocervical adenocarcinoma (CESC) was confirmed from the GEPIA online database." (PMID 34758823, 2021).
esophageal squamous cell carcinoma (8 papers, 2019 to 2024). Esophageal squamous cell carcinoma (ESCC) is a type of esophageal carcinoma (EC) that can affect any part of the esophagus, but is usually located in the upper or middle third. "HOTAIR can also regulate HK2 expression in esophageal squamous cell carcinoma by combining endogenous miR-125 and miR-143, and then regulate glycolysis of esophageal squamous cell carcinoma to affect the occurrence and development of tumors." (PMID 35093153, 2022). "The expression of HK2 in esophageal squamous cell carcinoma was higher than that in esophageal adenocarcinoma (P < 0.05)." (PMID 34708035, 2021). "A recent study has demonstrated that capsaicin has the power to inhibit tumor glycolysis in esophageal squamous cell carcinoma (ESCC) by acting on hexokinase-2 expression, an enzyme participating in the process of glycolysis, a mechanism that is involved in the rapid growth of cancer cells." (PMID 33379302, 2020). "Although most studies focused on HK2, some studies found that the expression of HK1 is connected with disease progression, invasion, and poor survival in patients with esophageal squamous cell carcinoma." (PMID 33029143, 2020).
laryngeal carcinoma (8 papers, 2017 to 2026). Carcinoma that arises from the laryngeal epithelium. "Previous studies have identified several SNPs associated with laryngeal cancer poor prognosis, and HK2 is one of the SNP-mediated oncogene targeted genes." (PMID 37834257, 2023). "The putative gene targeted by miR-125a-5p has been identified as HK2, while the expression levels of miR-125a-5p and HK2 were measured in laryngeal cancer tissues and cells using RT-PCR." (PMID 39224810, 2024). "Additionally, miR-125a-5p binding to HK2 modulates laryngeal cancer cell apoptosis." (PMID 39224810, 2024).
metastatic tumor (8 papers, 2012 to 2024). "In conclusion the present study supports a requirement for HK2 in PDAC tumorigenesis and metastasis that helps explain the associated findings of high HK2 expression in PDAC patients with metastatic disease." (PMID 28915575, 2017). "In our study, we found that the higher expression of HK2 in metastatic tumors, where tumor glycolysis increased, supported the elevated FDG uptake of tumors." (PMID 36677035, 2023). "Higher 18F-FDG uptake was demonstrated in metastatic tumors compared to primary tumors, supported by the significantly increased metastatic tumor protein expression of HK2, which is relevant to the upstream step of glycolysis." (PMID 36677035, 2023). "We found that 10 cases (29.4%) showed diffuse strong immuno-expression (grade 4) of HK2 in metastatic tumor cells and 7 cases (20.6%) revealed diffuse strong immuno-expression (grade 4) of GLUT1." (PMID 34249674, 2021). "All of these findings indicate that HK2 may be one of the glycolytic genes responsible for the metabolic switch from primary to metastatic tumors." (PMID 31212816, 2019). "Associations between increased HK2 expression, metastatic disease, and poor clinical outcomes have been observed in other cancers however a direct link between HK2 and metastasis has not been shown." (PMID 28915575, 2017). "HK2 was also overexpressed in fat and liver metastatic tumors." (PMID 22412968, 2012). "In the metastatic mice, the SUVmean of metastatic tumors was significantly higher than that of primary lung tumors in PET images, which was supported by elevated glycolytic protein expression of HK2 and PKM2." (PMID 36677035, 2023). "To understand the detailed changes in the cellular system between primary tumors and metastatic tumors, we conducted H&E staining, immunofluorescence staining of Ki-67, and Western blotting of Glut1, HK1, HK2, PKM2, and PC." (PMID 36677035, 2023).
Obesity (8 papers, 2013 to 2026). Accumulation of substantial excess body fat. "HK2 also phosphorylates glucose into glucose-6-phosphate and its increased expression is associated with obesity." (PMID 39860248, 2025). "Exposure of human granulosa cell line (HGrC1) to FF from women with PCOS and obesity was associated with a marked reduction in glycolytic capacity (p < 0.05) and decreased mRNA expression of key glycolytic regulators, including GLUT1, HK2 and LDHA (p < 0.05)." (PMID 41847445, 2026). "We note that Hk2 knockout did not completely phenocopy to the effect of obesity in mice and humans." (PMID 36920797, 2023).
osteoarthritis (8 papers, 2019 to 2026). A noninflammatory degenerative joint disease occurring chiefly in older persons, characterized by degeneration of the articular cartilage, hypertrophy of bone at the margins and changes in the synovial membrane. "Our findings demonstrated that DPSC-EVs represent a promising cell-free therapeutic strategy for TMJOA, exerting their protective effects by targeting HK2, thereby preserving chondrocyte viability and attenuating osteoarthritis development." (PMID 42072611, 2026). "Both HK1 and HK2 serve as the first rate-limiting enzyme in glycolysis, implicating their involvement in metabolic derangements in osteoarthritis chondrocytes." (PMID 37134114, 2023). "Of interest, HK2 is an inducible enzyme present only in the inflamed rheumatic tissues compared to osteoarthritis synovium." (PMID 31428089, 2019). "HK2 expression has been identified in fibroblast-like synoviocytes from osteoarthritis knees." (PMID 37134114, 2023). "Hexokinase 2 (HK2) has been a focus of osteoarthritis research in recent years." (PMID 37134114, 2023). "The expression of glycolytic related genes HK2 and GLUT1 was upregulated in osteoarthritis fibroblasts stimulated by Co2+, while no glycolytic related genes were upregulated in Cr3+-stimulated osteoarthritis fibroblasts." (PMID 41036386, 2025).
pancreatic adenocarcinoma (8 papers, 2020 to 2024). "For example, HOTAIR was reported to promote cancer cell energy metabolism in pancreatic adenocarcinoma by upregulating hexokinase-2." (PMID 37529795, 2022). "HOTAIR alters cancer cell energy metabolism in pancreatic adenocarcinoma by the upregulation of HK2." (PMID 33652661, 2021). "Overexpression of the lncRNA HOTAIR increased tumor cell proliferation, lactate production, glucose uptake, and ATP production in pancreatic adenocarcinoma by upregulating hexokinase-2 (HK-2)." (PMID 32765426, 2020). "Oncomine database analysis showed that HK2 expression in bladder, brain and CNS, esophageal, gastric, head and neck, kidney, ovarian, and pancreatic adenocarcinoma was higher than that in normal tissue samples." (PMID 34708035, 2021). "In a study on pancreatic adenocarcinoma (PAAD), a connection between glycolysis and the LINC02432/hsa-miR-98-5p/HK2 molecular triad was identified." (PMID 38872210, 2024).
B-cell lymphoma (7 papers, 2015 to 2023). "More importantly, HK2 inhibition by the HDAC inhibitor panobinostat remarkably ameliorated the cisplatin resistance of B-cell lymphoma cell lines." (PMID 37854321, 2023). "Altogether, our findings provide strong support for the direct contribution of HK2 in B-cell lymphoma development and suggest that HK2 is a key metabolic driver of the DLBCL phenotype." (PMID 29335581, 2018). "We previously reported that cyclin D1 inhibits mitochondrial activity in B-cell lymphoma, by competing with hexokinase 2 for binding to the voltage-dependent anion channel." (PMID 25881299, 2015). "Additionally, HK2 has been identified as a crucial factor in the pathology of malignant B-cell lymphomas." (PMID 38099309, 2023).
brain tumor (7 papers, 2015 to 2024). "The elevation of HK2 was also found in the most common malignant brain tumors." (PMID 33922649, 2021). "Recent studies have shown that 3-bromopyruvate, a hexokinase 2 (HK2) inhibitor, and its derivatives (pentyl 3-bromopyruvate ester [P-BrPE] and 3-bromo-2-oxopropionate-1-propyl ester [3-BrOP]) reduce the viability of CSCs and that knockdown of GLUT3 inhibits the growth of brain tumor CSCs." (PMID 25528771, 2015). "Overexpression of metabolic enzymes such as hexokinase 2 (HK2) that is required for metabolic reprogramming has been shown in GBM, but not in low grade brain tumor." (PMID 28630875, 2017).
lymph node metastasis (7 papers, 2016 to 2023). "In the present study, we found that deregulation of HK2 expression was frequently correlated with the progression of TSCC and that increased HK2 expression was associated with lymph node metastasis and reduced 5-year OS." (PMID 27926482, 2017). "In addition, we used an intrahepatic cholangiocarcinoma tissue microarray to investigate the correlations between FGFR1, VEGFR3 and HK2 expression and tumour-associated lymphangiogenesis and lymph node metastasis in patients with iCCA." (PMID 37433897, 2023). "The high expression of HK2 showed a significant positive correlation with the advanced stage of the tumor, lymph node metastasis, and worst survival in renal carcinoma patients." (PMID 35265223, 2022). "Our results revealed that the expression of HK2, lymph node metastasis, and tumor stage was significantly correlated with the OS rate of RCC patients in univariate analysis." (PMID 35265223, 2022). "In summary, our study suggests that lymph node metastasis and recurrence in OSCC are associated with increases in PD1 and glycolysis in CD4+ T cells; Hk2 may be a key enzyme in glycolysis contributing to the progression of metastatic lymph nodes in OSCC." (PMID 37270478, 2023). "Meanwhile, the miR-216b expression was found to be significantly lower and HK2 expression was higher in patients with a lesion size > 2 cm, lymph node metastasis (LNM) and at III stage than in those with lesion size ≤ 2 cm, without LNM and at I/II stage (p < 0.05)." (PMID 34345220, 2021). "Increased HK2 expression was associated with tumour stage, clinical stage, lymph node metastasis, but not pathological grade, and reduced overall survival." (PMID 27926482, 2017). "Among TSCC cases, the levels of HK2 were significantly higher in tumours of grade T3+4 than in those of grade T1+2, in tumours of grade CIII+IV than in those of grade CI+II, and in patients with lymph node metastasis than in those with no lymph node metastasis." (PMID 27926482, 2017).
oral cancer (7 papers, 2017 to 2025). "Overexpression of miR-143 causes the downregulation of HK2 protein in oral cancer, leading to a reduction in glucose consumption." (PMID 34830755, 2021). "Thus, elucidating the molecular mechanisms underlying HK2 dysregulation holds profound implications for the development of targeted therapies tailored for oral cancer." (PMID 38529190, 2024). "To elucidate the role of HK2 in cancer progression, we conducted qRT-PCR assays to compare its expression levels in oral cancer cell lines (FaDu and Cal27) with those in normal human foreskin (HFF-1) and embryonic kidney (HEK293) cells lines." (PMID 38529190, 2024). "The evaluation of the anti-proliferative activity of the inhibitors and their HK2 enzyme inhibitory activity provides crucial insights into their therapeutic potential against oral cancer." (PMID 38529190, 2024). "In conclusion, this work provides a foundation for tool compounds to study HK2 mediated effects in oral cancer." (PMID 38529190, 2024). "The studies have conclusively showed that H2 is a potent inhibitor of HK2 enzyme activity and an inducer of mitophagy which holds promise for developing effective therapies for oral cancer." (PMID 38529190, 2024). "Our data show that miR-143 complementary pairs to the 3′-UTR of HK2 in oral cancer cells, leading to the inhibition of glycolysis in vitro and in vivo." (PMID 28174335, 2017). "If Cal27 cells indeed exhibit a higher dependence on HK2-mediated glycolysis for their survival, targeting HK2 may represent a more effective therapeutic strategy for Cal27-derived oral cancers." (PMID 38529190, 2024). "Notably, HK2 is overexpressed in various cancers, including oral cancer, where it contributes to tumor growth, metastasis and therapeutic resistance as evidenced by Kaplan Meier survival analysis from TCGA." (PMID 38529190, 2024). "We identified HK2 as a direct target of miR-143 in oral cancer cells and tumor patients, suggesting inhibition of HK2 by miR-143 might be a new therapeutic approach for the treatments of oral cancer." (PMID 28174335, 2017). "Moreover, knockdown of HK2 by siRNA in oral cancer cells inhibited glucose metabolism, proliferation and migration." (PMID 28174335, 2017). "We identified hexokinase 2 (HK2) as a direct target of miR-143 in oral cancer cells." (PMID 28174335, 2017). "In addition, we demonstrated restoration of HK2 in miR-143 overexpressing oral cancer cells could increase the tumorigenesis and invasion of oral cancer cells in vitro." (PMID 28174335, 2017). "In this study, we investigated the effect of HK2 inhibition on MMP in FaDu and Cal27 oral cancer cells." (PMID 38529190, 2024). "Hypoxia related genes NF-κB, HIF1α, HK2, and PFKL were upregulated in CAFs activated by oral cancer-derived EVs." (PMID 37745296, 2023). "Glycolytic enzymes Aldoa, Hk2, Tpi1, Pgam2, Pfkl, and Pkm2 as well as the PKA-AMPK pathway genes Prkaa2, Pde4a, Pde10a, Ywhag, and Crebbp were downregulated by BRBs during oral cancer chemoprevention." (PMID 31336728, 2019).
endometrial cancer (6 papers, 2020 to 2023). Primary or metastatic malignant neoplasm involving the endometrium (mucous membrane that lines the endometrial cavity). "For example, Lnc-DLEU2 can drive epithelial-mesenchymal transition and glycolysis in endometrial cancer through HK2 by competitively binding to miR-455 and by modulating the enhancer of zeste 2 polycomb repressive complex 2 subunit (EZH2)/miR-181 pathway." (PMID 35156508, 2022). "The long non-coding RNA (lncRNA) SNHG16 promoted the proliferation of endometrial carcinoma cells and glycolysis by competitively sponging miR-490-3p and upregulating HK2, which is miR-490-3p’s target gene." (PMID 35887124, 2022). "Moreover, HK2 drives glycolysis and autophagy, thus conferring cellular protection in endometrial cancer." (PMID 37524692, 2023). "HK2 knock down in endometrial cancer cells impaired cell proliferation and self-renewal ability, and the RNA-seq of HK2-siRNA cells indicated that HK2 may promoted cancer stemness by metabolic pathways." (PMID 37143105, 2023). "Moreover, HK2 has higher expression in endometrial cancer vs. normal tissue based on the CPTAC database of all races." (PMID 35887124, 2022). "HK2-siRNA was transfected to Ishikawa and HEC1A cells to explore the roles and molecular mechanism of HK2 in endometrial cancer." (PMID 37143105, 2023). "Endometrial cancer cell lines Ishikawa and HEC1A were transfected with HK2-siRNA (HK2-siRNA-1, HK2-siRNA-2 and HK2-siRNA-3) or negative control." (PMID 37143105, 2023).
fatty liver disease (6 papers, 2018 to 2025). A reversible condition wherein large vacuoles of triglyceride fat accumulate in liver cells via the process of steatosis. "The interactions between saroglitazar and ferulic acid with different enzymes and metabolites involved in metabolic dysfunction-associated fatty liver disease (MASLD), such as SORD, HK1, HK2, MgATP, KHK, HK3, ALDOB, ALDOC, and fructose-1-phosphate (F1P)." (PMID 40130107, 2025). "In the PTEN-null mice, HK2, PKM2, and other glycolytic enzymes are overexpressed via P13K/AKT2/PPARγ axis, which partially account for the susceptibility to fatty liver and hepatocellular carcinoma of PTEN-null mice." (PMID 34526911, 2021). "Moreover, adenoviral-mediated overexpression of HK2 and PKM2 promoted liver steatosis." (PMID 37107193, 2023). "Moreover adenoviral-mediated overexpression of HK2 and PKM2 promotes liver growth and liver steatosis, which may bridge the enhanced glycolysis with carcinogenesis in fatty liver." (PMID 34526911, 2021). "Furthermore, it has been previously demonstrated that PPARγ could activate PI3K/AKT pathway, which then regulated the novel and direct targets HK2 and PKM2, leading to hepatic steatosis and cell proliferation." (PMID 32612951, 2020). "Moreover, PPARγ plays important roles in glucose metabolism by regulating the expression of hexokinase 2 (HK2) and the M2 isoform of pyruvate kinase (PKM2), resulting in massive liver steatosis in phosphatase and tensin homologs deleted on chromosome 10 (PTEN)-null mice." (PMID 29954129, 2018).
prostate tumor (6 papers, 2015 to 2024). "In another study of a Pten-deficient prostate tumor mouse model, systemic deletion of HK2 inhibited tumor growth and metastasis." (PMID 33753739, 2021). "Our observations reveal reduced glucose uptake and lactate production within prostate tumor tissues under XHP intervention, accompanied by a decline in the expression of glycolytic enzymes (GLUT1, HK2, and PKM2)." (PMID 38994113, 2024).
pulmonary fibrosis (6 papers, 2020 to 2025). Chronic progressive interstitial lung disorder characterized by the replacement of the lung tissue by connective tissue, leading to progressive dyspnea, respiratory failure, or right heart failure. "Treatment with the HK2 inhibitor lonidamine reduced the expression of pro-fibrotic genes and stabilized lung function in a mouse model of bleomycin-induced pulmonary fibrosis." (PMID 38203486, 2023). "In pulmonary fibrosis, TGF-β–induced HK2 expression has been shown to promote fibrotic remodeling, indicating its potential as a therapeutic target in fibrotic lung diseases." (PMID 40643524, 2025). "TGF‐β signalling activates hexokinase 2 (HK2) to enhance glycolysis and lung fibrosis through YAP/TAZ." (PMID 38700015, 2024). "Due to the similar metabolic reprogramming observed in myofibroblasts and cancer cells, it is also possible that HK2 may accumulate in the nucleus of IPF cells and influence targets involved in promoting pulmonary fibrosis." (PMID 38203486, 2023).